RORA (RAR related orphan receptor A)
Diseases named in the same sentence as RORA in open-access papers (continued):
Sharing a sentence is not in itself a finding about the gene and the disease.
cancer (continued). "Furthermore, we found that RORA was significantly underexpressed in eight cancer types but was overexpressed in KIRC, suggesting that the biological impacts of expressional alterations in melatonergic genes are dependent on the cancer type." (PMID 33842355, 2021). "As RORα regulates cancer, inflammation, circadian rhythm, and metabolism, it not only functions as a transcriptional effector but also as a sensitive sensor that captures and reconstructs distinct changes in the cellular environment into transcriptional responses." (PMID 34588606, 2021). "Furthermore, we believed that RORα activation may enhance the activation of CD8+ T cells, leading to the inhibition of cancer progression." (PMID 32610705, 2020). "With the exception of three clusters of NRs representing NR classes I (cluster I: RORC, VDR, PPARA, NR1D1, THRA, RORA, NR1H3; cluster II: RARB, PPARG, THRB) and III (cluster III: ESR1, PGR, AR, ESRRG), NR class was not a good determinate of NR expression patterns in the different cancer types." (PMID 32024906, 2020). "Furthermore specific clock genes Rev-Erbα and RORα deficient mice have negative effects on the development of and activation of dendritic cell and other antigen presenting cells (APC) critical to pathways involved with immune mediated cancer cell targeting." (PMID 38090501, 2023). "These approaches are important for understanding the regulation of specific noncanonical pathways in which drugs do not modulate RORα via LBDs, suggesting that a mechanism-based drug administration strategy may be useful for specifically inhibiting cancer activity." (PMID 34588606, 2021). "Additionally, because the expression levels of CYP27B1, VDR, CYP11A1, and RORα/γ in cancer cells progressively decline during cancer progression the effectiveness of vitamin D-based therapy may be limited to only early stages, but not late stages, of cancer." (PMID 29657326, 2018). "Several studies revealed a role for a noncanonical RORα pathway in cancer that does not involve RORE binding, but in which RORα functions as a transcriptional cofactor." (PMID 26878025, 2015).
infection (18 papers, 2011 to 2025). The state of being infected such as from the introduction of a foreign agent such as serum, vaccine, antigenic substance or organism. "Primary and secondary memory T cells that are sufficient or deficient of RORα were induced by adoptive transfer of naïve OT-I T cells to recipient mice and subsequent infection with Listeria monocytogenes expressing ovalbumin (LM-OVA)." (PMID 40895530, 2025). "Additionally, the recall responses to antigen stimulation or infection, including the proliferative response and the production of effector molecules, were also similar between RORα-deficient and control memory T cells." (PMID 40895530, 2025). "However, DR3 expression was almost completely abolished due to RORα deficiency in effector T cells (1–2 weeks after primary infection) and secondary memory T cells." (PMID 40895530, 2025). "Furthermore, either adenovirus encoding RORα infection or RORα ligands administration increased the formation of capillary tubes in human umbilical vascular endothelial cells." (PMID 36834872, 2023). "RORα was overexpressed via infection with RORα-encoding adenovirus to determine whether RORα regulates the gene expression of pro-inflammatory factors." (PMID 38036731, 2023). "Therefore, it is possible that T-cell-specific deletion of RORα, and/or inhibition of RORα activity may render the host more susceptible to dissemination of enteric bacteria or infection by pathogenic bacteria, including Citrobacter rodentium." (PMID 33397953, 2021). "Tnfrsf25 showed the biggest fold change among downregulated genes in the RORα-deficient KLRG1+ effector T cells isolated at days 7 and 10 after primary infection." (PMID 40895530, 2025). "Gene expression analysis of the four treatment group comparisons was used to examine the differences in host immune responses of the wild-type (WT) and the RORα knock-out (KO) mice at 10 days post-infection with N. brasiliensis." (PMID 40559579, 2025). "Consistently, Rorα DN significantly reduced neutrophil recruitment to infection or tail amputation sites." (PMID 35309302, 2022). "We first determined gene expression in the hypothalamic tissues that isolated from PVN area of offspring, and found that infection of either ERβ or RORA lentivirus significantly increased mRNA levels, respectively, indicating a successful gene manipulation." (PMID 35370982, 2022). "The infection and knockdown efficiency was measured after adenovirus injection by immunofluorescence staining of RORα." (PMID 34584074, 2021). "The levels of the Rora, SPARC, PLG, G6PC, NR1D2 and AGRP mRNAs were measured by qRT-PCR 24 h, 48 h and 72 h after infection of HepG2 cells with either Ad-RORα or control Ad-GFP." (PMID 21818335, 2011). "In summary, our data indicated that the miR-99/RORα axis functions as a novel modulator in the acute stage of neutrophil recruitment and is potentially a novel target in preventing and treating acute inflammatory diseases and infections." (PMID 35309302, 2022). "Infection of ERβ lentivirus completely, while RORA expression partly, reversed this effect." (PMID 35370982, 2022). "Interestingly, the genes whose expression was modulated in cells stably over-expressing RORα also showed altered expression in cells in which RORα was transiently over-expressed following infection with a RORα adenoviral vector." (PMID 21818335, 2011). "Furthermore, S. venezuelensis-infection-induced resistance against N. brasiliensis was impaired in ILC2-deficient mice, suggesting that the protective phenotype of Sv-exp mice requires RORα-dependent innate lymphoid cells." (PMID 30283458, 2018). "The IFN-γ, T-bet, RORα, and IL17A genes were up-regulated and peaked at 6 h (p < 0.05) after infection and immunization, then declined and then rose again at 48 h." (PMID 36363767, 2022). "A strong interaction between dietary APS and NE infection was observed in relation to TLR2, IFN-γ, TNF-α, IL-6, IL-10, RORα and Foxp3 (P < 0.05) in jejunum." (PMID 35265068, 2022).
infection (continued). "The mRNA expression of RORα and amphiregulin was not changed after 1 or 7 days of H pylori–SS1 infection." (PMID 28210674, 2015). "Similarly, a broadly used strategy to delete Rorα using IL-7RCre deleter mice in CD127-expressing cells (e.g., T cells, ILCs, B cells) resulted in effective ILC2 depletion without obvious effects on Th2 cells during infection-dependent type 2-mediated lung inflammation." (PMID 32117319, 2020).
metabolic disease (16 papers, 2015 to 2025). A congenital disorder (due to inherited enzyme abnormality) or acquired (due to failure of a metabolically important organ) disorder resulting from an abnormal metabolic process. "Risk for development of metabolic disorders increases with age, thus we decided to study the effect of RORα deletion in aging." (PMID 28744254, 2017). "Notable, MTNR1B gene showed a more prominent association with clusters related to metabolic diseases, including glucose metabolism, compared to related genes such as MTNR1A or RORA." (PMID 40697662, 2025). "Indeed, studies on RORα in the context of metabolism have demonstrated the impact of RORα in signaling pathways associated with lipid and glucose metabolism, alongside influencing the low-grade chronic inflammation that is often a hallmark of metabolic disease." (PMID 33767712, 2021). "In this study, we have described a novel mouse model that we used to characterize the role of RORα in metabolic disorders." (PMID 28744254, 2017). "This creates some difficulty in interpretation of the role of RORα in models of metabolic disease where feeding and muscle function is a critical component of the pathophysiology." (PMID 28744254, 2017). "Moreover, RORα expression correlates with the onset of metabolic diseases such as HFD-induced nonalcoholic steatohepatitis, coronary heart disease with concomitant abdominal obesity, and metabolic syndrome." (PMID 34588606, 2021). "Recently, studies have shown that metabolic disorders affected by circadian rhythms might be attributed to RORα and RORγ, partly because of their modulation in both circadian and metabolic diseases." (PMID 29904382, 2018). "Therapeutic strategies designed to modulate RORα activity may be beneficial for the treatment of metabolic disorders." (PMID 28757615, 2017). "Therefore, RORα may be considered a key target in the development of agents to treat various metabolic diseases." (PMID 34588606, 2021). "Indeed, ILC2s are widely associated with a lean phenotype and decrease in number in obese adipose tissue, which suggests that RORα may play differential roles in regulating metabolic disease dependent upon the cell type in which it is expressed." (PMID 32973801, 2020). "Therefore, it has been proposed that therapeutic strategies modulating RORα activity may be beneficial for the treatment of metabolic disorders." (PMID 32610705, 2020). "Our study presents a new model to study the role of RORα in metabolic disorders without the complexity of a cerebellar deficit that may alter normal feeding behavior and physical activity." (PMID 28744254, 2017). "The discrepancy between findings in RORα gene expression in rodent and human studies not only indicates that is more required to clarify the role or RORα in metabolic liver disease, but also that rodent studies may not always represent the ideal model for mimicking human metabolic disease." (PMID 37642240, 2023).
cardiovascular diseases (6 papers, 2011 to 2024). "In the context of cardiovascular diseases, RORα is cardioprotective owing to it having antioxidant properties." (PMID 39518891, 2024). "Further characterization of the mechanisms of RORα action will not only identify RORα target genes and provide additional insight into their normal physiological functions but also determine their protective roles in cardiovascular diseases." (PMID 36834872, 2023). "This review summarizes the understanding and potential effects of RORα in the cardiovascular system and then analyzes current advances, limitations and challenges, and further strategy for RORα-related drugs in cardiovascular diseases." (PMID 36834872, 2023). "These potential strategies offer a good opportunity to provide targeted treatment for cardiovascular diseases by relevant RORα drugs." (PMID 36834872, 2023). "These candidates of novel RORα-related active compounds are of great significance in the treatment of cardiovascular diseases." (PMID 36834872, 2023). "This review mainly summarizes protective roles and possible mechanisms of RORα against cardiovascular diseases." (PMID 36834872, 2023). "Altogether, these studies substantiate the inherent protective role of RORα in the mitigation of cardiovascular diseases and other injuries and highlight the importance of RORα with respect to the regulation of autophagy and preservation of cellular homeostasis." (PMID 39518891, 2024). "Identifying direct transcriptional targets of RORα may lead to the discovery of novel stimulators of autophagy and mitophagy that can be used for the treatment of a variety of cardiovascular diseases." (PMID 39119356, 2024). "By the aid of multidisciplinary research, breakthrough progress on RORα-related drugs to combat cardiovascular disorder may appear." (PMID 36834872, 2023). "All these studies suggest that RORα might offer potential therapeutic approaches for cardiovascular diseases." (PMID 36834872, 2023). "Finally, since RORα is generally protective not only in the heart but also in other organs, small molecule agonists that selectively stimulate RORα should have wide therapeutic applications not limited to cardiovascular disease." (PMID 39119356, 2024). "Overall, by the aid of multidisciplinary research involving materials science, clinical medicine, pharmacology, pharmaceutical chemistry, and pharmaceutical pharmaceutics, breakthrough progress on RORα-related drugs to combat cardiovascular disorder may appear." (PMID 36834872, 2023).
neurological disorders (5 papers, 2013 to 2022). "Importantly, other IN genes such as Rorα and Rorβ are potential targets of MiR34/449, so whether MiR34/449 miRNAs regulate a battery of spinal INs and if disruption of those pathways account for diverse neurological disorders are interesting topics for further study." (PMID 33787491, 2021).
immune diseases (4 papers, 2021 to 2025). "Therefore, a deeper understanding of cell type-specific and context-dependent regulation of RORα is likely needed to inform strategies to combat RORα-associated immune diseases." (PMID 36243007, 2022). "Preclinical data suggest that melatonin acts through the RORA and TLR4/TRIF pathways, making it a particularly interesting therapeutic target in the context of immune disorders associated with sleep deprivation." (PMID 40724980, 2025). "For instance, melatonin also acts through the RORA and TLR4/TRIF pathways, making it a particularly interesting therapeutic target in the context of immune disorders associated with sleep deprivation." (PMID 40724980, 2025). "Targeting RORA to restore circadian rhythm could be an innovative therapeutic approach to mitigate immune dysfunction and improve patient outcomes." (PMID 40274894, 2025).
psychiatric disorder (4 papers, 2017 to 2023). A disorder characterized by behavioral and/or psychological abnormalities, often accompanied by physical symptoms. "The Retinoid-related Orphan Receptor Alpha (RORA) gene encodes a nuclear hormone receptor that is involved in circadian rhythm regulation and has been implicated in various psychiatric disorders." (PMID 37626936, 2023).
bacterial infection (3 papers, 2021 to 2022). "RORa has proven a target in LPS-associated septic shock in mice, as well as surviving bacterial infection following severe burns injury, in rodents." (PMID 35880253, 2022). "Taken together, RORα plays an essential role in regulating neutrophil activation and the defense against bacterial infection." (PMID 35309302, 2022). "We then investigated whether RORα is required for defending against bacterial infection using P. aeruginosa." (PMID 35309302, 2022). "Inhibiting RORα, but not the closely related RORγ, reduced chemotaxis of zebrafish and primary human neutrophils without causing cell death, and increased susceptibility of zebrafish to bacterial infection." (PMID 35309302, 2022).
neurodegenerative disease (3 papers, 2022 to 2025). A disorder of the central nervous system characterized by gradual and progressive loss of neural tissue and neurologic function. "Previous studies have confirmed the anti-inflammatory and metabolic regulatory functions of RORα in other neurodegenerative diseases, but its role in HIE remains largely unexplored." (PMID 40799648, 2025). "However, the function of RORα in the pathogenesis of neurodegenerative diseases remains much unclear." (PMID 35803929, 2022).
retinopathy (3 papers, 2020 to 2023). "Previously in an oxygen-induced retinopathy model we found that genetic deficiency of RORα regulates macrophage polarization and retinal inflammation with dampened TNFα." (PMID 36626253, 2023). "Previously in an oxygen-induced retinopathy model and in Vldlr−/− mice with spontaneous subretinal neovascularization, we found that either genetic loss or pharmacological inhibition of RORα suppressed retinal neovascularization in neonatal mice." (PMID 36626253, 2023). "In addition, RORα deficiency stimulated a pro-inflammatory environment in the CNV choroid in this study, whereas in the oxygen-induced retinopathy model, RORα deficiency lead to an anti-inflammatory profile in neonatal retinas." (PMID 36626253, 2023). "RORα is a critical upstream regulator of SEMA3E expression, and controls SEM3E-dependent neurovascular coupling in retinopathy." (PMID 32098361, 2020). "RORα directly binds to a specific ROR response element on the promoter of Sema3e and negatively regulates Sema3e transcription, which can impact retinopathy development via signaling through its receptor complexes located on pathological neovessels." (PMID 32098361, 2020). "In contrast, RORα suppressed the expression of suppressors of cytokine signaling 3 (SOCS3), a negative regulator of inflammation, and deletion of RORα protects against oxygen-induced proliferative retinopathy in a murine model." (PMID 35309302, 2022).
neurodevelopmental disorder (2 papers, 2024 to 2025). A behavioral and cognitive disorder with onset during the developmental period that involves impaired or aberrant development of intellectual, motor, or social functions. "Disruptions in this mechanism can lead to the hypermethylation of critical gene promoters, such as the retinoic acid-related orphan receptor alpha (RORA), which has been implicated in neurodevelopmental disorders like autism spectrum disorder (ASD)." (PMID 40001584, 2025). "TCF12 is essential for neuronal migration in cortical development, and RORA play crucial roles of cerebellar and systemic abnormalities observed in neurodevelopmental disorders." (PMID 39184089, 2024).
brain diseases (1 paper, 2020). "Even though, the exact role of RORα in ERK1/2 pathway still needs to be investigated in successive research work, which is important for the exploration of the pathogenesis of BTI and related inflammation brain diseases." (PMID 31959187, 2020).
central nervous system disorder (1 paper, 2025). A disease involving the central nervous system. "Given the limited treatment options for central nervous system diseases like HIE, the therapeutic strategy proposed here to activate RORα provides a promising approach for controlling neuroinflammation and potentially improving long-term outcomes in HIE patients." (PMID 40799648, 2025). "Future studies should examine the dose-response effects, safety, and long-term impact of RORα, optimize drug delivery systems through preclinical trials, and investigate potential combination therapies to advance the clinical application of RORα in HIE and other central nervous system disorders." (PMID 40799648, 2025).
heart disease (1 paper, 2021). "Taken together, these studies suggest that activation of RORα in vivo could represent a novel therapeutic approach to heart disease." (PMID 34756888, 2021).
respiratory diseases (1 paper, 2023). "In fact, several genes are involved in respiratory diseases (BMALl1, FOXa2, CKIε, PER3, TIM, RORα, Clock, PER2-3, BHLHE40-41, REV-ERBα, and CRY1-2)." (PMID 38067152, 2023).
RORA also shares sentences with these, for which no sentence is quoted: Ataxia (5 papers); rheumatoid arthritis (3); systemic lupus erythematosus (3); type 1 diabetes (3); acute myocardial infarction (2); cervical carcinoma (2); dermatitis (2); Huntington disease (2); inflammation (2); lung squamous cell carcinomas (2); metastatic melanoma (2); multiple myeloma (2); non-small cell lung carcinoma (2); oral squamous cell carcinoma (2); papillary renal cell carcinoma (2); rectal cancer (2); ulcerative colitis (2); acute coronary syndrome (1); age (1); Age-related cataract (1); Airway obstruction (1); Allergy (1); alopecia areata (1); anxiety disorder (1); Atrophy (1); B-cell chronic lymphocytic leukemia (1); bladder cancer (1); bladder urothelial carcinoma (1); blood pressure (1); brain tumors (1).
A further 45 diseases each share a sentence with RORA in 1 paper.